SHBG (sex hormone binding globulin)
Diseases named in the same sentence as SHBG in open-access papers (continued):
Sharing a sentence is not in itself a finding about the gene and the disease.
anorexia nervosa (4 papers, 2015 to 2025). A disorder most often seen in adolescent females characterized by a refusal to maintain a minimally normal body weight, an intense fear of gaining weight, a disturbance in body image, and, in postmenarcheal females, the development of amenorrhea. "However, recent studies have shown that serum SHBG levels were linked to the nutritional status of individuals with primary infertility, anorexia nervosa, kwashiorkor, and polycystic ovary syndrome." (PMID 39020340, 2024). "In contrast to the population with increased BMI, patients with anorexia nervosa present elevated serum levels of SHBG, which could be connected with menstrual cycle and reproductive system disturbances." (PMID 40427034, 2025). "Eating disorders such as anorexia nervosa, in turn, tend to increase SHBG levels, which may also affect hormonal and menstrual disorders in this group of patients." (PMID 40427034, 2025). "Thus, the concentration of SHBG rises with age and the levels of SHBG are low in obese patients and extremely high in patients with anorexia nervosa." (PMID 31105806, 2015). "Notably, SHBG levels are increased in conditions such as anorexia nervosa and kwashiorkor." (PMID 39020340, 2024).
Arthritis (4 papers, 2020 to 2023). Inflammation of a joint. "The potential causal effects of SHBG concentrations on the three types of arthritis (OA, RA, and AS) were estimated by IVW analyses." (PMID 32423484, 2020). "In this study, we investigated the potential association between genetically predicted SHBG concentrations and three types of arthritis (OA, RA, and AS)." (PMID 32423484, 2020). "Little evidence was provided for the sex-specific causal effect of SHBG levels on the three types of arthritis." (PMID 32423484, 2020). "The site-specific associations between SHBG level and OA as well as the sex-specific associations between SHBG level and three types of arthritis were further explored." (PMID 32423484, 2020). "However, the mechanisms by which SHBG plays causal roles in the development of arthritis require further investigations." (PMID 32423484, 2020). "Besides these factors, the sex hormone-binding globulin (SHBG) has been reported to be a risk factor of these three types of arthritis." (PMID 32423484, 2020). "Cognizant to this, measurement of SHBG in serum could be valuable in the clinical assessment of arthritis especially in early screening and prevention of OA and RA." (PMID 32423484, 2020). "Evidently, measurement of SHBG in serum could be valuable in the clinical assessment of arthritis especially in early screening and prevention of OA and RA." (PMID 32423484, 2020). "The potential interactions between SHBG concentrations and arthritis remain unclear." (PMID 32423484, 2020). "However, the role of circulating SHBG in arthritis has not been well established by these studies." (PMID 32423484, 2020).
Cushing syndrome (4 papers, 2016 to 2025). Cushing's syndrome (CS) encompasses a group of hormonal disorders caused by prolonged and high exposure levels to glucocorticoids that can be of either endogenous (adrenal cortex production) or exogenous (iatrogenic) origin. "SHBG levels are reduced in patients with Cushing’s syndrome and in patients treated with glucocorticoids." (PMID 26761949, 2016). "Low SHBG together with adrenocorticotropic hormone (ACTH)-mediated testosterone production may cause virilization in children, and contribute to delayed puberty, and anovulation and oligo-amenorrhea in ACTH-dependent Cushing’s syndrome." (PMID 26761949, 2016). "Luteinising hormone (LH) and sex hormone binding globulin (SHBG) both increase in PCOS, whereas they fall in concentration in Cushing syndrome." (PMID 37189516, 2023).
female infertility (4 papers, 2023 to 2025). Diminished or absent ability of a female to achieve conception. "The IVW analysis demonstrated a causal relationship between SHBG and female infertility (OR = 0.906, 95% CI = 0.837–0.98, P = 0.014)." (PMID 38848344, 2024). "We found evidence supporting a causal effect of SHBG on the risk of female infertility (OR=0.854; 95% CI, 0.793–0.920; P=2.853e-05)." (PMID 39006368, 2024). "IVW analysis indicated a significant association between genetically predicted SHBG levels and female infertility." (PMID 39006368, 2024). "This discovery suggests the potential role of SUA and SHBG as biomarkers for assessing female infertility risk, although further research is needed to validate these findings." (PMID 39006368, 2024). "Our findings demonstrate causal links between high SUA and increased risk of female infertility mediated by hormonal factors such as SHBG and TT." (PMID 39006368, 2024). "In the subsequent step, we assessed the causal effect of SHBG on the risk of female infertility using genetic tools for SHBG." (PMID 39006368, 2024). "Overall, SHBG was significantly associated with female infertility." (PMID 38848344, 2024). "Currently, the causal relationship between SHBG and female infertility remains unclear." (PMID 38848344, 2024). "In the forward MR analysis, examining the relationship between SUA levels (as an exposure factor), sex hormone-related phenotypes (as mediators), and female infertility (as an outcome factor), we identified unidirectional causality between SUA and SHBG." (PMID 39006368, 2024). "Calculating the indirect effect of SUA levels on female infertility through SHBG, we found a mediated effect of 0.041 (95%CI, 0.015 to 0.074; P=0.006), with a mediated proportion of 27.93% (95%CI,0.302%, 0.310%)." (PMID 39006368, 2024). "Baseline characteristics of Serum uric acid levels, sex hormone-related phenotypes (Sex hormone-binding globulin, Total testosterone, Estradiol) and female infertility datasets." (PMID 39006368, 2024). "Given the pivotal role of sex hormone-related phenotypes in addressing elevated SUA and female infertility, particularly the potential protective mediation of elevated SHBG, it becomes essential to comprehensively elucidate the impact of sex hormone-related phenotypes on female infertility." (PMID 39006368, 2024). "Using VWI-based MR analysis, we found that SHBG was negatively correlated with female infertility." (PMID 38848344, 2024). "However, the IVW analysis revealed no causal relationship between SHBG levels and female infertility with a tubal origin (OR = 0.857, 95% CI = 0.705–1.043, P = 0.123)." (PMID 38848344, 2024). "However, SHBG showed no causal effect relationship on male or female infertility with a tubal origin." (PMID 38848344, 2024).
Gynecomastia (4 papers, 1983 to 2024). Abnormal development of large mammary glands in males resulting in breast enlargement. "Other causes of gynecomastia are renal failure, which causes hypotestosteronemia and hyperprolactinemia, and liver failure, which is associated with increased SHBG levels and consequent reduction in testosterone levels and impaired estrogen metabolism." (PMID 35566722, 2022). "Therefore, in the case of gynecomastia, a careful evaluation of the gonadal hormone profile (LH, FSH, total testosterone, SHBG, albumin, and E2), the hepatic and renal function, and a testicular ultrasound should be carried out for an early diagnosis of these diseases." (PMID 35566722, 2022).
Hepatitis (4 papers, 2013 to 2025). Inflammation of the liver. "Although HCC progression was phenotypically suppressed in SHBG mice compared with that in WT mice, which is similar to our published data, EE2 could expose SHBG mice to HCC risk by triggering markedly pronounced hepatitis, fibrosis, and compensatory proliferation with AR activation." (PMID 34830439, 2021). "Macromolecular target prediction using the SwissTargetPrediction indicated that these molecules could also target enzymes associated with metabolic diseases (HSD11B1), could be aromatase inhibitors (CYP19A1), and exhibited anti-hepatitis and antihyperthyroidism (SHBG) activities, among others." (PMID 38675469, 2024).
Hypercholesterolemia (4 papers, 2021 to 2025). An increased concentration of cholesterol in the blood. "Furthermore, the IVW method also indicates that each increase of 1-SD in SHBG is associated with a reduced risk of high cholesterol (OR 0.72; 95% CI 0.64–0.82), hypercholesterolemia (OR 0.71; 95% CI 0.61–0.82), and CHD (OR 0.73; 95% CI 0.63–0.86)." (PMID 38796576, 2024).
hyperprolactinemia (4 papers, 2015 to 2024). Abnormally high level of prolactin in the blood. "Since prolactin has been demonstrated as an inhibitor of SHBG, hyperprolactinemia observed in the present study may contribute to the reduced plasma levels of SHBG in HU group." (PMID 33663539, 2021). "Prolactin might influence the metabolism of SHBG by its inhibiting hormonal influences and decrease of SHBG in hyperprolactinemia." (PMID 26635963, 2015). "Both groups were comparable with respect to age, reasons for hyperprolactinemia, smoking, BMI, blood pressure, HOMA1-IR, and plasma levels of glucose, total prolactin, monomeric prolactin, macroprolactin, FSH, SHBG, thyrotropin, ACTH and IGF-1." (PMID 37685540, 2023). "While increased SHBG and hyperprolactinemia were observed, the severity of hormonal changes did not always align with disease progression." (PMID 39650982, 2024).
leiomyoma (4 papers, 2017 to 2022). A well-circumscribed benign smooth muscle neoplasm characterized by the presence of spindle cells with cigar-shaped nuclei, interlacing fascicles, and a whorled pattern. "Only few cells in normal myometrial tissues, and mostly co-localized with sex hormone-binding globulin (SHBG) and oxytocin (OT) in leiomyoma samples, which may be linked to growth of leiomyomas." (PMID 31759347, 2019). "The causal relationships estimated from MVMR (including LBW and BMI) were consistent with the univariable IVW analysis (LBW) for SHBG, bio-T, and menarche, except for leiomyoma." (PMID 36035116, 2022).
liver cancer (4 papers, 2024 to 2025). An epithelial or non-epithelial malignant neoplasm that arises from the liver. "A doubling of 4-androstenedione concentration was associated with a 50% reduction in liver cancer risk (OR = 0.50), while sex hormone-binding globulin (SHBG) was associated with a 31% increase (OR = 1.31)." (PMID 39410050, 2024). "The UK Biobank study showed that total T and SHBG, but not free T, were significantly associated with liver cancer in men, but not in women." (PMID 41228208, 2025). "Moreover, higher concentrations of sex hormone-binding globulin (SHBG) and testosterone have been linked to increased gastric and liver cancer risks in men." (PMID 40839628, 2025).
liver fibrosis (4 papers, 2018 to 2026). "Multivariate analysis showed that only SHBG was independently associated with both liver fibrosis scores (APRI p < 0.0001; FIB-4 p = 0.002)." (PMID 33515211, 2021). "Multivariate analysis showed that SHBG was independently associated with both liver fibrosis scores." (PMID 33515211, 2021). "Lower SHBG levels in men may lead to higher free testosterone levels, resulting in an increased risk of liver fibrosis." (PMID 39698035, 2024). "SHBG level was associated to liver fibrosis independently of age, BMI, HCV ab or HIV duration." (PMID 33515211, 2021). "For in vivo studies we used wild-type and human SHBG transgenic mice developing liver fibrosis induced by carbon tetrachloride (CCl4)." (PMID 42278422, 2026). "Taken together, we demonstrate for the first time that SHBG protects against liver fibrosis by promoting collagen degradation via the TGF-β1/MMPs/TIMP1 pathway." (PMID 42278422, 2026). "Our data suggest that in compensated forms T levels are maintained within normal range by an increase of LH production secondary to higher SHBG levels induced by liver fibrosis." (PMID 33515211, 2021). "In contrast, circulating SHBG levels were increased in proportion to the severity of hepatic fibrosis (F1, 84.0 ± 33.3 nmol/L; F2, 94.5 ± 51.6 nmol/L; F3, 153.2 ± 87.4 nmol/L; F4, 168.3 ± 42.1 nmol/L)." (PMID 30487676, 2018). "In the present work, we have examined whether SHBG could protect against development of liver fibrosis." (PMID 42278422, 2026). "However, circulating sex hormone-binding globulin levels were significantly increased in proportion to the severity of hepatic fibrosis." (PMID 30487676, 2018). "Moreover, SHBG overexpression reduced the CCl4 induced liver fibrosis in both male and female mice." (PMID 42278422, 2026). "The elevation of SHBG levels with no alteration in total testosterone levels may account for calculated lower free testosterone levels in CLD-C patients with advanced hepatic fibrosis." (PMID 30487676, 2018). "In addition, the relationship between sex hormones and SHBG levels and Non Alcoholic Steato Hepatitis (NASH), Non Alcoholic Fatty Liver Disease (NAFLD) and liver fibrosis has been reported in some studies, although with non-conclusive data." (PMID 33515211, 2021).
lymphoma (4 papers, 2009 to 2023). A malignant (clonal) proliferation of B- lymphocytes or T- lymphocytes which involves the lymph nodes, bone marrow and/or extranodal sites. "Accordingly, LH, FSH, total testosterone and SHBG blood tests should be offered to male lymphoma survivors as a part of their regular follow-up to detect any possible signs of androgen deficiency." (PMID 35326591, 2022). "Thus, an altered testosterone-to-sex-hormone-binding-globulin ratio in lymphoma survivors should be considered in future studies." (PMID 37256215, 2023). "Gonadal function was assessed in male lymphoma survivors based on serum hormone levels (LH, FSH, testosterone, SHBG), and was related to treatment, age and observation time." (PMID 19156143, 2009).
malnutrition (4 papers, 2012 to 2024). Inadequate nutrition resulting from poor diet, malabsorption, or abnormal nutrient distribution. "This study has also noted a relationship between elevated serum SHBG levels and an increased risk of malnutrition in men and postmenopausal women with T2DM." (PMID 39020340, 2024). "Serum SHBG levels are correlated with nutritional indicators and the risk of malnutrition in men and postmenopausal women with T2DM." (PMID 39020340, 2024). "SHBG levels exhibit correlations with nutritional indicators, and elevated serum SHBG levels are linked with an augmented risk of malnutrition in male and postmenopausal female T2DM patients." (PMID 39020340, 2024). "Accordingly, this cross-sectional study was designed to elucidate the correlation between serum SHBG levels and nutritional indicators and the risk of malnutrition in men and postmenopausal women with T2DM." (PMID 39020340, 2024). "Our findings revealed a significant association between elevated serum SHBG levels and heightened risk of malnutrition exposure in males and postmenopausal women with T2DM." (PMID 39020340, 2024). "Furthermore, an upward trend in SHBG levels was observed with increasing risk of malnutrition exposure in both males (29.14 ± 13.38, 41.52 ± 21.58, and 49.99 ± 25.21 nmol/L, respectively) and postmenopausal women (32.82 ± 16.51, 43.92 ± 19.32, and 50.47 ± 26.49 nmol/L, respectively) (P < 0.05)." (PMID 39020340, 2024). "The findings imply that males and postmenopausal females with T2DM may associated with a significant risk of malnutrition exposure, with elevated serum SHBG levels being independently correlated with an increased malnutrition exposure risk in these demographics." (PMID 39020340, 2024). "On the other hand, malnutrition such as anorexia and Kwashiorkor patients with protein and energy malnutrition show increased plasma SHBG levels compared with control normal weight individuals." (PMID 34335746, 2021). "Compared to their without malnutrition exposure risk counterparts, the with malnutrition exposure risk group exhibited significantly elevated levels of SHBG and HbA1c and reduced C-peptide, triglycerides, uric acid, hemoglobin, IGF-1, AST, ALT, weight, BMI, albumin, prealbumin, and transferrin." (PMID 39020340, 2024).
Miscarriage (4 papers, 2019 to 2025). A pregnancy that ends at a stage in which the fetus is incapable of surviving on its own, defined as the spontaneous loss of a fetus before the 22th week of pregnancy. "Weight reduction increases the sex hormone binding globulin (SHBG) concentration, improves ovarian function and fertility, and reduces miscarriages." (PMID 38388374, 2024).
periodontitis (4 papers, 2023 to 2024). An acute or chronic inflammatory process that affects the tissues that surround and support the teeth. "Studies have shown that men with lower levels of bioavailable testosterone affected by sex hormone-binding globulin have a higher risk of periodontitis." (PMID 39331593, 2024). "Our results are in concordance with another similar study in 2015 based on the NHANES III, which found that low SHBG was inversely associated with periodontitis." (PMID 36864844, 2023). "Our research suggested that males with lower bioavailable testosterone levels affected by SHBG were at a higher risk of periodontitis." (PMID 36864844, 2023). "Our research suggested that males with lower bioavailable testosterone levels affected by sex hormone-binding globulin were at a higher risk of periodontitis." (PMID 36864844, 2023). "This investigation found that TT levels and E2 levels were unrelated to periodontitis, while SHBG levels were significantly positively associated with periodontitis, and FT, FAI, and bioavailable testosterone were all significantly negatively correlated with periodontitis in men." (PMID 36864844, 2023). "The decrease in bioavailable testosterone affected by SHBG may be one of the risk factors for the occurrence of periodontitis." (PMID 36864844, 2023). "In males, the periodontitis group had higher SHBG levels and lower bioavailable testosterone levels than the non-periodontitis group." (PMID 36864844, 2023). "Inversely, the periodontitis group had a lower SHBG level than the non-periodontitis group in females." (PMID 36864844, 2023). "This study found that male subjects under the age of 50 with higher SHBG levels were more likely to develop periodontitis (P for trend = 0.014), while those over the age of 50 did not (P for trend = 0.144)." (PMID 36864844, 2023). "We explored the mediation effects of sex hormones (testosterone, estradiol, SHBG, and TT/E2) on the relationship between PFOS and periodontitis in NHANES 2013–2014." (PMID 38360594, 2024).
venous thromboembolism (4 papers, 2013 to 2023). Occlusion of the lumen of a vein by a thrombus that has migrated from a distal site via the blood stream. "Can changes in sex hormone binding globulin predict the risk of venous thromboembolism with combined oral contraceptive pills?" (PMID 24648858, 2013). "Rg: Genetic correlation; SHBG: Sex hormone-binding globulin; TT: Total testosterone; BT: Bioactive testosterone; VTE: Venous thromboembolism; PE: Pulmonary embolism; DVT: Deep vein thrombosis." (PMID 37880771, 2023).